SLIT2 (slit guidance ligand 2)
Diseases named in the same sentence as SLIT2 in open-access papers (continued):
Sharing a sentence is not in itself a finding about the gene and the disease.
intestinal tumor (2 papers, 2015 to 2019). "All the results suggested that the specific blocking of Slit2/Robo1 signaling inhibited tumor growth and metastasis during intestinal tumor development." (PMID 31242633, 2019). "We next investigated the impact of Slit2/Robo1 signaling on the initiation and development of intestinal tumors using the Slit2 transgenic (Slit2-Tg) mice model in which Slit2 is genetically overexpressed." (PMID 25605242, 2015). "In addition, the expression levels of Slit2 in tumor tissues and serum were both gradually increased with intestinal tumor development." (PMID 31242633, 2019). "In addition, the ApcMin/+ spontaneous intestinal adenoma mice were employed to further confirm the serum levels of Slit2 during intestinal tumor development." (PMID 31242633, 2019). "We showed that Slit2 and Robo1 are overexpressed in intestinal tumors and may contribute to tumor generation." (PMID 25605242, 2015). "Along with the increased expression of pSrc (Tyr 416) in the intestinal tumor tissues of the ApcMin/+;Slit2 mice and DMH/DSS-Slit2 mice, activation of Slit2/Robo1 signaling was also found to be associated with a marked decrease in the expression of E-cadherin in the tumor tissues." (PMID 25605242, 2015). "According to our previous findings, Slit2/Robo1 signaling might regulate tumor growth by activation of the Wnt pathway, and induce tumor metastasis by TGF-β/Smads signaling and Hakai-mediated EMT during intestinal tumor development." (PMID 31242633, 2019).
intrahepatic cholangiocarcinoma (2 papers, 2023). A carcinoma that arises from the intrahepatic bile duct epithelium in any site of the intrahepatic biliary tree. "SLIT2 has also been identified as a driver of tumor dissemination and tumor-associated neutrophil infiltration in relapsed human intrahepatic cholangiocarcinoma." (PMID 36469291, 2023).
medulloblastoma (2 papers, 2016 to 2024). A malignant, invasive embryonal neoplasm arising from the cerebellum. "Slit2 was also shown to inhibit medulloblastoma cell invasion in multiple models in vitro and this effect was rescued by the ectodomain of Robo1." (PMID 39456164, 2024).
mental disorder (2 papers, 2020 to 2025). A disease that has its basis in the disruption of mental process. "Notably, SLIT2 and KCNQ3, previously linked to psychiatric disorders but without specific cell-type associations, exhibit cell-type–specific dysregulation." (PMID 40053590, 2025).
multicystic dysplastic kidney (2 papers, 2021 to 2023). Multicystic dysplastic kidney (MCDK) is a congenital anomaly of the kidney and urinary tract (CAKUT) in which one or both kidneys (unilateral or bilateral MCDK respectively) are large, distended by multiple cysts, and non-functional. "Variants in ROBO2, and likely also variants in SLIT2 and the downstream small GTPase activator SRGAP1, lead to CAKUT (mostly multicystic dysplastic kidneys, MCDK) in humans." (PMID 33625646, 2021).
nasopharyngeal carcinoma (2 papers, 2015 to 2019). A carcinoma arising from the nasopharyngeal epithelium. "For example, miR-218 can suppress nasopharyngeal cancer progression through down-regulation of BIRC5 (survivin) and the SLIT2 (slit guidance ligand 2)-ROBO1 (roundabout guidance receptor 1) pathway." (PMID 26553452, 2015).
primary biliary cirrhosis (2 papers, 2021 to 2023). "It has been proved that the hepatic expression of SLIT2 was significantly increased in patients with primary biliary cirrhosis and in bile duct ligation mouse model." (PMID 35111704, 2021). "Furthermore, serum levels and hepatic expression of SLIT2 are significantly elevated in patients with primary biliary cirrhosis (PBC)." (PMID 37238655, 2023).
proliferative diabetic retinopathy (2 papers, 2011 to 2017). Advanced retinopathy due to diabetes mellitus characterized by the formation of new vessels in the retina. "The concentration of Slit2 protein in human eyes was measured by enzyme-linked immunosorbent assay in 27 eyes with proliferative diabetic retinopathy and 28 eyes in control group." (PMID 28973045, 2017). "Our findings that the vitreous of eyes with proliferative diabetic retinopathy have stronger Slit2 expression suggests that Slit2 is a novel player in angiogenesis." (PMID 28973045, 2017). "The expression of Slit2 mRNA, Robo1 mRNA, and VEGF mRNA was significantly higher in human fibrovascular proliferative diabetic retinopathy membranes than in the control membranes." (PMID 28973045, 2017). "Because rodents do not develop proliferative diabetic retinopathy, we selected the patients with proliferative diabetic retinopathy (PDR) to examine the roe of Slit2 and Robo1 in proliferative stage." (PMID 28973045, 2017). "Additionally, FVMs and vitreous fluid from patients both with proliferative diabetic retinopathy (PDR) and without (control) were used to investigate the expression of Slit2 and Robo1 in the proliferative stage of DR." (PMID 28973045, 2017).
prostate tumor (2 papers, 2024 to 2025). "Moreover, recent studies have demonstrated that phytochemical treatments can increase SLIT2 and ROBO1 expression and inhibit DU145 prostate tumor cells." (PMID 40508075, 2025).
renal fibrosis (2 papers, 2019 to 2024). A final common manifestation of a wide variety of chronic kidney diseases characterized by glomerulosclerosis and tubulointerstitial fibrosis. "N-terminal, but not C-terminal, Slit2 is required to inhibit TGF-β-induced renal fibrosis." (PMID 30717252, 2019).
Stroke (2 papers, 2020 to 2025). Sudden impairment of blood flow to a part of the brain due to occlusion or rupture of an artery to the brain. "Previous studies have shown that the Slit2-Robo1 pathway contributes to cell migration and supports neurological recovery after stroke." (PMID 40265103, 2025). "It is not clear how Slit2 modulates GABAergic function in stroke." (PMID 33028376, 2020).
abscesses (1 paper, 2023). "Exposure of HMEC-1 to hypoxia, typically found in advanced S. aureus SSTI-associated abscesses, also phenocopied the SLIT2 expression pattern in vitro." (PMID 37773612, 2023).
acute myeloid leukemia (1 paper, 2022). Acute myeloid leukemia (AML) is a group of neoplasms arising from precursor cells committed to the myeloid cell-line differentiation. "Previously, our study reported that hypermethylation of the SLIT2 promoter was associated with disease progression in myelodysplastic syndrome (MDS) and predicted poor clinical outcome in both MDS and acute myeloid leukemia (AML)." (PMID 36411451, 2022).
Alzheimer disease (1 paper, 2020). A progressive, neurodegenerative disease characterized by loss of function and death of nerve cells in several areas of the brain leading to loss of cognitive function such as memory and language. "Our previous experimental results showed Alzheimer's disease-like alterations and increased permeability of the blood–brain barrier in Slit2-overexpressing transgenic (Slit2-Tg) mice aged 8–9 months." (PMID 33613201, 2020).
atherosclerosis (1 paper, 2021). A disease characterized by the build-up of fatty material and calcium deposition in the arterial wall resulting in partial or complete occlusion of the arterial lumen. "We further found that peripheral blood mononuclear cells from patients with coronary artery disease expressed lower surface levels of Robo-1, and that in atherosclerosis-prone mice, Slit2 inhibited recruitment of circulating monocytes into nascent atherosclerotic lesions." (PMID 33574432, 2021). "By inhibiting recruitment of monocytes into early atherosclerotic lesions, and the subsequent binding and internalization of oxLDL by macrophages, Slit2 could represent a potent new tool to combat individual steps that collectively result in progression of atherosclerosis." (PMID 33574432, 2021).
atrial septal defect (1 paper, 2019). Interauricular communication is a congenital malformation characterized by a communication between the atrial chambers of the heart. "This is the first study to find an association of SLIT2 and SLIT3 with predisposition to human CHD, although, of note, a recent study identified ROBO1 loss-of-function SNVs in cases with TOF and septal defects." (PMID 31613678, 2019).
autoimmune disease (1 paper, 2021). A disorder resulting from loss of function or tissue destruction of an organ or multiple organs, arising from humoral or cellular immune responses of the individual to their own tissue constituents. "SLIT2 glycoprotein has been described to regulate the inflammatory response and participate in autoimmune diseases." (PMID 34007851, 2021).
brain glioma (1 paper, 2022). A malignant glioma that involves the brain. "Survival time for brain glioma patients with decreased SLIT2 mRNA expression is shorter than for that for those with a normal expression of SLIT2." (PMID 35053460, 2022).
cardiac ischemia (1 paper, 2020). "The secreted glycoprotein Slit2, previously known as an axon guidance cue, has recently been found to protect tissues in pathological conditions; however, it is unknown whether Slit2 functions in cardiac ischemia–reperfusion (IR) injury." (PMID 32292352, 2020).
CNS DLBCL (1 paper, 2022). "Some highly mutated genes in primary CNS DLBCL, such as MUC16, ODZ4 and SLIT2 reported in the previous studies were not covered in our present NGS panel." (PMID 35223507, 2022).
cognitive decline (1 paper, 2020). "Furthermore, Slit2 overexpression protected against glymphatic system and BBB dysfunction, attenuated local neuronal loss, and ultimately prevented cognitive decline induced by parietal microinfarcts." (PMID 33028376, 2020).
dementia (1 paper, 2021). Loss of intellectual abilities interfering with an individual's social and occupational functions. "These proteins were associated with increased dementia risk, with the fully adjusted hazard ratio per 1 SD being 1.16 (95% confidence interval 1.05 to 1.28) for SLIT2, 1.13 (1.00 to 1.27) for CHSTC, and 1.04 (0.97 to 1.13) for AMD." (PMID 34407988, 2021). "In age, sex, and ethnicity adjusted analysis of combined data from the Whitehall subcohort and ARIC, higher levels of SLIT2, CHSTC, and AMD were associated with increased dementia risk, or, conversely, lower protein levels were associated with lower dementia risk." (PMID 34407988, 2021). "We identified three proteins, SLIT2, AMD, and CHSTC for which plasma levels were found to be significantly lower among participants with cognitive stimulation at work, whereas high levels of these proteins were found to be associated with increased dementia incidence." (PMID 34407988, 2021).
diabetic nephropathy (1 paper, 2022). "Slit-2/Robo1 signaling is involved in early diabetic nephropathy and may be an effective therapeutic target for abnormal angiogenesis in early diabetic nephropathy." (PMID 35813663, 2022).
diffuse large B-cell lymphoma (1 paper, 2022). "Reduced mRNA expression of SLIT2 is associated with advanced clinical stage and worse overall survival in diffuse large B cell lymphoma." (PMID 35053460, 2022).
ductal carcinoma (1 paper, 2015). "Our results demonstrated that Invasive ductal carcinoma patients with low expression of Slit2 or Robo1 exhibited worse prognosis and brain-specific metastasis, but not liver, bone or lung." (PMID 26400100, 2015).
endothelial dysfunction (1 paper, 2017). In vascular diseases, endothelial dysfunction is a systemic pathological state of the endothelium (the inner lining of blood vessels) and can be broadly defined as an imbalance between vasodilating and vasoconstricting substances produced by (or acting on) the endothelium. "A study discovered that LPS-induced endothelial dysfunction was mediated through the Slit2-Robo4 pathway and downregulation of Slit2 reduced the expression of miR-218." (PMID 29207683, 2017).
endotoxemia (1 paper, 2020). "SLIT2/ROBO1-axis triggers proinflammatory signaling, and SLIT2/ROBO4-axis alleviates inflammation in endothelial cells during endotoxemia." (PMID 32760720, 2020).
Ewing sarcoma (1 paper, 2022). A small round cell tumor that lacks morphologic, immunohistochemical, and electron microscopic evidence of neuroectodermal differentiation. "Slit2 silencing strongly inhibited both anchorage-dependent and anchorage-independent growth as well as sphere formation of Ewing sarcoma cells." (PMID 36533189, 2022). "Silencing of Slit2 strongly inhibited anchorage-dependent and anchorage-independent growth of Ewing sarcoma cells." (PMID 36533189, 2022).
gastric tumor (1 paper, 2025). "During early gastric tumor progression, methylation of CpG islands inactivates SLIT1, SLIT2 and SLIT3." (PMID 40508075, 2025).
gestational diabetes (1 paper, 2022). Carbohydrate intolerance first diagnosed during pregnancy. "The purpose of this study was to explore the expression of Slit-2 in maternal peripheral blood and neonatal cord blood of gestational diabetes mellitus (GDM) patients and its potential importance in disease progression." (PMID 35813663, 2022).
glomerulonephritis (1 paper, 2019). A renal disorder characterized by damage in the glomeruli. "Furthermore, Slit2 expression has been found to decrease in a rat glomerulonephritis model, and the inhibition of Slit2 expression in the early stages of the disease has been found to accelerate inflammation." (PMID 30717252, 2019).
head and neck cancer (1 paper, 2004). A primary or metastatic malignant neoplasm affecting the head and neck. "Frequent 4p allele loss has been reported in cancers that demonstrate SLIT2 methylation such as lung, breast and NB, and also in cancers in which SLIT2 methylation status has not been investigated including colorectal, bladder and head and neck cancers." (PMID 14735202, 2004).
Hypoglycemia (1 paper, 2023). A decreased concentration of glucose in the blood. "Placenta glucose transfer, DNA methylation from umbilical cord blood and neonatal blood, the same source of different cells, and Slit-2/Robo1 signaling all might be involved in the pathogenesis of UACBG predicting neonatal hypoglycemia." (PMID 38129821, 2023).
inflammatory bowel disease (1 paper, 2019). A spectrum of small and large bowel inflammatory diseases of unknown etiology. "Downregulating Slit2 expression may be due to an increase in promoter methylation as a higher Slit2 methylation is associated with an inflammation status in inflammatory bowel disease." (PMID 30717252, 2019).
ischemia reperfusion injury (1 paper, 2019). Adverse functional, metabolic, or structural changes in ischemic tissues resulting from the restoration of blood flow to the tissue (reperfusion), including swelling; hemorrhage; necrosis; and damage from free radicals. "In addition, the expression of Slit2 decreases in the kidneys after ischemia-reperfusion injury (IRI)." (PMID 30717252, 2019).
keloid (1 paper, 2022). An irregularly shaped, elevated mark on the skin caused by deposits of excessive amounts of collagen during wound healing. "PPAR and axon guidance pathways might be inhibited in keloid lesions because of the downregulated expression of PPARγ and Slit2, respectively." (PMID 35709140, 2022).
kidney tumour (1 paper, 2004). "Except for SKRC 45 and SKRC 47 (both unmethylated for SLIT2), SLIT2 expression was significantly increased in the kidney tumour cell lines after 5-aza-dC treatment." (PMID 14735202, 2004).
lymph node metastasis (1 paper, 2015). "Univariate analysis indicated that Slit2 expression, Robo1 expression, pathological grade, lymph node metastasis and cTNM were significantly associated with shortened OS." (PMID 26400100, 2015). "In multivariate Cox regression analysis, Slit2 and Robo1 were both independent prognostic factors for OS, when stratified by tumor size, pathological stage, lymph node metastasis, and cTNM." (PMID 26400100, 2015).
myelodysplastic syndrome (1 paper, 2022). A clonal hematopoietic disorder characterized by dysplasia and ineffective hematopoiesis in one or more of the hematopoietic cell lines. "Previously, our literature reported that slit guidance ligand 2 (SLIT2) promoter methylation was associated with disease progression and indicated a poor prognosis in patients with myelodysplastic syndrome." (PMID 36411451, 2022).
myocardial infarction (1 paper, 2025). Gross necrosis of the myocardium, as a result of interruption of the blood supply to the area, as in coronary thrombosis. "Following myocardial infarction (MI), Slit2 transiently increases in the infarct border zone seven days post-MI but declines significantly after one month." (PMID 41203011, 2025).
Osteochondroma (1 paper, 2018). A common, benign cartiliginous neoplasm arising from the metaphysis of bone. "Next, we detected the expression patterns of ROBO1 and SLIT2 in OS (n = 40) and osteochondroma (OC) (n = 10) tissue specimens by IHC staining." (PMID 29523788, 2018).
Osteopenia (1 paper, 2025). Osteopenia is a term to define bone density that is not normal but also not as low as osteoporosis. "In contrast, specific deletion of Slit2 in neurons caused severe osteopenia due to impaired bone formation." (PMID 41090361, 2025).